TYMS (thymidylate synthetase)
Diseases named in the same sentence as TYMS in open-access papers (continued):
Sharing a sentence is not in itself a finding about the gene and the disease.
hepatocellular carcinoma (22 papers, 1986 to 2025). A malignant tumor that arises from hepatocytes. "TYMS expression is upregulated in hepatocellular carcinoma, and its overexpression has been associated with poor prognosis and tumor progression." (PMID 38473844, 2024). "Conversely, increased expression of TYMS in hepatocellular carcinoma cells and patient samples was associated with hepatocellular carcinoma progression and resistance to 5-FU." (PMID 39353904, 2024). "Enhanced TYMS activity has been shown to be associated with reduced risk for hepatocellular cancer." (PMID 23826176, 2013). "The association of UBE2C with RBP7, alongside other upregulated genes such as TK1 and TYMS, underscores its potential role in hepatocellular carcinoma progression and highlights UBE2C as a critical target for therapeutic intervention in this context." (PMID 41301068, 2025). "According to a prior study, FOXM1-induced upregulation of TYMS promotes the progression of hepatocellular carcinoma." (PMID 38719775, 2024). "For example, the transcription factor FOXM1 can directly promote the transcription of TYMS, which can lead to the resistance of hepatocellular carcinoma cells to chemotherapeutic agents such as 5-FU." (PMID 39353904, 2024). "Among them, TYMS, KIF2C, UBE2C, and HJURP are associated with unfavorable prognosis in hepatocellular carcinoma, possibly due to the malignant growth of cells." (PMID 37035748, 2023). "The purpose of this study was to develop and validate a radiomics nomogram for predicting thymidylate synthase (TYMS) status in hepatocellular carcinoma (HCC) by using Gd-DTPA contrast enhanced MRI." (PMID 37848807, 2023). "We identified 4 hub genes, namely, LAMA4, POLA2, RAD51, and TYMS, which were used as the final variables, and found that AdaBoostClassifie was the best algorithm for the classification and diagnosis model of hepatocellular carcinoma." (PMID 37051625, 2023). "Furthermore, AKR1B10 and TYMS were upregulated in hepatocellular carcinoma patients compared to NAFLD." (PMID 38720280, 2024). "Also, the expression of YBX1 mRNA significantly positively correlated with RRM2, TK1, and TYMS mRNA expression in 374 human hepatocellular carcinoma samples (TCGA)." (PMID 32587247, 2020). "In addition, TYMS inhibits the growth of human hepatocellular carcinoma cells and triggers DNA damage through proteasome-dependent pathway degradation, but its ubiquitination site and type are mainly unknown." (PMID 39353904, 2024). "Among them, CDK1, CHEK1, TYMS, KIF11, MMP12, TK1 and CA12 were differentially highly expressed in hepatocellular carcinoma tissues." (PMID 38842135, 2024).
pancreatic cancer (21 papers, 2005 to 2025). "They concluded the study by proposing TYMS as a diagnostic and prognostic biomarker for patients with pancreatic cancer." (PMID 37373974, 2023). "In summary, the results of the present study indicate that the TYMS genetic polymorphism rs11280056 is significantly associated with grade 1–2 neurotoxicity among pancreatic cancer patients treated with FOLFIRINOX." (PMID 35056973, 2021). "The present study is the first report demonstrating the significant association between TYMS genetic polymorphism, specifically TYMS rs11280056, and neurotoxicity among pancreatic cancer patients treated with FOLFIRINOX." (PMID 35056973, 2021). "In addition, expression of the YY genotype in the methionine synthase reductase (MTRR) H595Y SNP and the 3Rc/3Rc genotype in thymidylate synthase (TYMS) also increased the risk for development of pancreatic cancer." (PMID 29474406, 2018). "Elevated expression of TYMS has been reported in pancreatic cancer and is negatively correlated with the overall survival and recurrence-free survival of patients." (PMID 38719775, 2024). "Overexpression of TYMS and IGFBP5 has been reported to be associated with shorter survival time and poorer disease outcomes in human pancreatic cancer and urothelial carcinoma, respectively." (PMID 36139323, 2022). "This study shows that IP 5-FU can penetrate pancreatic tumour and adjacent tissues along the metastatic route, and metabolize to FdUMP which is needed for inhibition of TYMS." (PMID 34132895, 2021). "Overexpression of TYMS in pancreatic cancer leads to a decrease in overall survival and relapse-free survival, which is a biomarker for diagnosis and prognosis of pancreatic cancer." (PMID 34141464, 2021). "5-FU, a classical anti-metabolite, inhibits thymidylate synthase (TYMS) and is widely used for anti-cancer therapy of colon and pancreatic cancers." (PMID 23965981, 2013). "Intriguingly, TYMS inhibitors like 5-FU have successfully prevented tumor progression and improved immune responses in many types of tumors, such as colorectal, gastric and pancreatic cancer." (PMID 36034466, 2022). "TYMS is a biomarker of pancreatic cancer, which is up-regulated in pancreatic cancer." (PMID 36532716, 2022). "Only TYMS expression correlated between pancreatic tumour and tissue (r = 0.60, p = 0.032)." (PMID 34132895, 2021). "The correlation found between dUr levels in plasma, pancreatic tumour, and pancreatic tissue as well as the increased dUr level in plasma after resection, indicates a possibility to use plasma dUr as a surrogate marker for TYMS inhibition." (PMID 34132895, 2021). "While the MTHFR A222V, MTRR H595Y, and TYMS 3Rc SNPs have previously been shown to be associated with pancreatic cancer, the studies did not include measurements of serum or RBC folate levels." (PMID 29474406, 2018). "Thus, one reason for TYMS overexpression in pancreatic tumour might be DNA hypomethylation." (PMID 34132895, 2021).
ovarian carcinoma (19 papers, 2008 to 2025). A malignant neoplasm originating from the surface ovarian epithelium. "The 3′ untranslated region of TYMS has predicted binding sites for several microRNA families, and altered expression of several microRNAs has been reported in ovarian carcinoma (both serous and unspecified type) when compared with normal tissue." (PMID 25978957, 2015). "In addition, we have demonstrated that the basal transcription of TYMS mRNA is the key factor required for up-regulation of hTS in drug-treated ovarian cancer cells." (PMID 23056627, 2012). "Altogether, our data indicate that constitutive TYMS mRNA transcription, cell cycle-induced hTS regulation and hTS enzyme stability are the three key mechanisms responsible for 5-fluorouracil induced up-regulation of human thymidylate synthase expression in the two ovarian cancer cell lines studied." (PMID 23056627, 2012). "The strongest links were observed between TYMS, RRM1, and DNA metabolic process-related terms, underscoring their role in proliferation and genomic maintenance in ovarian cancer." (PMID 41009727, 2025). "We first confirmed that gene expression of FOLR1 (for FRα) and of members of the folate signalling pathway (FOLH1, TYMS and DHFR), were elevated in ovarian cancer cell lines and ovarian cancer tissues, compared to normal tissues." (PMID 36402875, 2023). "Therefore, targeting enzymes involved in pyrimidine metabolism, such as DHODH and thymidylate synthetase (TYMS), has emerged as a promising approach for the development of novel cancer therapies for peritoneal cancers, including ovarian cancer." (PMID 37233659, 2023). "Among the 50 drugs screened by the community, 13 drugs were used as therapy for ovarian cancer and all of the drug could target to the YES1 or TYMS." (PMID 31068972, 2019).
rectal cancer (14 papers, 2006 to 2025). A primary or metastatic malignant neoplasm that affects the rectum. "We have previously reported that a low level of TYMS gene expression in tumor tissues before CRT was associated with the response in rectal cancer patients receiving preoperative CRT including S-1 or UFT." (PMID 28417167, 2017). "However, the association between tumor response and ABCC3 and TYMS gene expression remained significant even after excluding rectal cancer patients who underwent preoperative radiotherapy." (PMID 40357991, 2025). "Specifically, ABCC3 and TYMS expression in rectal cancer were notably different in group 1 (p = 0.045 and p = 0.0056, respectively), whereas lower RFC‐1 expression was observed in both group 1 (p = 0.011) and group 2 (p = 0.0087)." (PMID 40357991, 2025). "Separately, in locally advanced rectal cancer, CTCs expressing thymidylate synthase (TYMS) and RAD23 homolog B (RAD23B) were identified as markers of resistance to chemotherapy and radiotherapy." (PMID 40565003, 2025). "Given the potential influence of preoperative radiotherapy on ABCC3 and TYMS expression, the statistical analysis was repeated after excluding rectal cancer patients who received radiotherapy." (PMID 40357991, 2025). "Data retrieved from the GEPIA database revealed a significant upregulation of TYMS mRNA expression in colorectal and rectal cancer tissues compared to normal tissues." (PMID 39744483, 2025). "In rectal cancer, previous studies have demonstrated that the low expression TYMS gene correlates with the pathological response to 5-Fluorouracil (5-FU)-based NCRT." (PMID 34207124, 2021). "On the other hand, a study on 30 patients with locally advanced rectal cancer reported that monitoring of protein markers such as thymidylate synthase (TYMS) and excision repair protein, RAD23 homolog B (RAD23B) in CTCs can help to predict resistance to chemotherapy/radiotherapy." (PMID 35292091, 2022). "Therefore, the gene expression levels of four genes, HIF1A, MTHFD1, GGH and TYMS, in tumor tissues before CRT may be useful for predicting the efficacy of preoperative CRT including S-1 or UFT/LV in patients with rectal cancer." (PMID 28417167, 2017).
lung adenocarcinoma (13 papers, 2012 to 2025). A carcinoma that arises from the lung and is characterized by the presence of malignant glandular epithelial cells. "LINC01667 can act as a sponge to regulate genes such as CCNB1, CEP55, MKI67, and TYMS, and ultimately affect the progression of lung adenocarcinoma." (PMID 34458133, 2021). "We found that miR-140-3p inhibited the proliferation, migration, invasion and angiogenesis of lung adenocarcinoma cells via targeting TYMS." (PMID 34818974, 2021). "Expression of TYMS (thymidylate synthase) was also higher in subgroup F, which is in good agreement with previous studies showing that higher expression of TYMS is significantly associated with poorer prognosis in lung adenocarcinoma." (PMID 22970185, 2012).
melanoma (13 papers, 2007 to 2025). A malignant, usually aggressive tumor composed of atypical, neoplastic melanocytes. "In this study, we found that NOD2 negatively regulated TYMS expression and activity in melanoma and promoted its K48-linked ubiquitination, thereby enhancing the degradation of TYMS through the ubiquitin-proteasome system." (PMID 39353904, 2024). "Further, TYMS is a Myc-regulated gene and TYMS overexpression was previously implicated in compensating for Myc loss and driving proliferation in Myc-knockdown melanoma cells." (PMID 32224870, 2020). "One of the probands (family 5) who carried TYMS exonic missense variant (c.480A>T [p.Gln160His]) has shown a severe adverse response to topical 5-FU when undergoing treatment for her squamous carcinoma and melanoma in her leg." (PMID 35931051, 2022). "However, the reasons for the dysregulation of TYMS in melanoma and its underlying mechanisms remain unclear." (PMID 39353904, 2024). "To understand the role of NOD2 in melanoma, we identified TYMS as a critical gene regulated by NOD2." (PMID 39353904, 2024). "Employing autophagy inhibitors or NOD2 overexpression in conjunction with autophagy inhibitors effectively curtailed melanoma progression, potentially serving as a mechanism by which TYMS and PLK1 influence melanoma." (PMID 39353904, 2024). "NOD2 suppresses melanoma development by inhibiting the TYMS/PLK1 signaling axis." (PMID 39353904, 2024). "Also, the significance of implementing NOD2 and the TYMS/PLK1 signaling axis was evaluated as targets for therapeutic intervention in melanoma." (PMID 39353904, 2024). "Our results indicate that overexpression of NOD2 could reduce the TYMS level and thus inhibit melanoma cell resistance to chemotherapeutic drugs." (PMID 39353904, 2024). "NOD2 may affect the biological behavior of melanoma cells by regulating the expression and activation status of TYMS and PLK1." (PMID 39353904, 2024). "NOD2 acts by regulating the TYMS/PLK1 signaling axis in melanoma." (PMID 39353904, 2024). "We hypothesized that NOD2 may influence chemoresistance in melanoma through the TYMS/PLK1 signaling axis." (PMID 39353904, 2024). "For example, the cell cycle-associated gene network hub TYMS is a target of 5-fluorouracil, a drug that has been studied in melanoma in the past but has not proved generally successful in melanoma patient populations." (PMID 22536322, 2012). "NOD2 may function in melanoma by regulating the expression and activities of TYMS and PLK1." (PMID 39353904, 2024). "Therefore, reducing TYMS expression and activity may inhibit melanoma malignant progression and reduce resistance to chemotherapeutic agents." (PMID 39353904, 2024). "It is possible that those melanoma patients with high expression of RNAs that are clustered with/downstream of TYMS in our analysis, indicating active molecular pathways involving TYMS, may be better candidates for topical 5-fluorouracil treatment than other patients." (PMID 22536322, 2012). "By upregulating NOD2 expression, we successfully inhibited melanoma growth and confirmed that NOD2 diminished melanoma ability to resist chemotherapeutic drugs by reducing TYMS level and activity." (PMID 39353904, 2024). "Melanoma cells and an in vivo model of sh-NOD2-1, we reconfirmed that NOD2 knockdown upregulated the protein levels of TYMS, PLK1, and p-PLK1." (PMID 39353904, 2024). "To further explore the potential of the TYMS/PLK1 signaling axis in combination therapy, we have investigated the effects of combining a PLK1 inhibitor (BI6727) with 5-FU or CAP in melanoma." (PMID 39353904, 2024). "Using the GEPIA database, we found that the expression of TYMS and PLK1 were significantly upregulated in melanoma." (PMID 39353904, 2024). "In summary, combination therapy for melanoma cell progression is an effective therapeutic strategy that can enhance the therapeutic effect by targeting NOD2, TYMS, and PLK1." (PMID 39353904, 2024).
melanoma (continued). "NOD2 inhibits thymidylate synthase (TYMS) expression by promoting K48-type ubiquitination modification of TYMS, thereby decreasing the resistance of melanoma cells to 5-fluorouracil (5-FU) and capecitabine (CAP)." (PMID 39353904, 2024). "Overall, our research highlights the protective role of NOD2 in melanoma and suggests that targeting NOD2 and the TYMS/PLK1 signaling axis is a high-profile therapy that could be a prospect for melanoma treatment." (PMID 39353904, 2024). "By disrupting cell cycle progression and inducing DNA damage, TYMS may alter PLK1 expression and activity, affecting processes such as proliferation, apoptosis, and EMT in melanoma." (PMID 39353904, 2024). "Furthermore, NOD2 overexpression in combination with TYMS inhibition and combination therapy targeting TYMS and PLK1 showed synergistic inhibition of melanoma proliferation and migration." (PMID 39353904, 2024).
prostate carcinoma (13 papers, 2015 to 2025). A carcinoma that arises from epithelial cells of the prostate gland. "The results of our study identify high TYMS expression as a strong prognostic feature in prostate cancers, which is strikingly linked to certain chromosomal deletions." (PMID 25762627, 2015). "In summary, our study identifies high TYMS expression as a strong and independent prognostic feature in prostate cancer, which is tightly linked to certain chromosomal deletions." (PMID 25762627, 2015). "The results of our study demonstrate that TYMS overexpression is strongly linked to the subset of aggressive prostate cancers characterized by early PSA recurrence and molecular features of chromosomal instability." (PMID 25762627, 2015). "Also for prostate cancer, some studies involving 52–172 patients have suggested that TYMS expression levels may be linked to unfavorable tumor phenotype." (PMID 25762627, 2015). "Both PCA3 (previously known as DD3) and TYMS have been shown to be overexpressed in prostate cancer, and TYMS was reported as correlating with aggressiveness." (PMID 38473871, 2024). "TYMS is more frequently expressed in patients with clinically advanced prostate cancer than in patients with advanced prostate cancer." (PMID 35003215, 2021). "In prostate cancers, cytoplasmic TYMS staining was observed in 72.9% of 10,223 interpretable cancer cases." (PMID 25762627, 2015). "In this study TYMS was analyzed by immunohistochemistry on a tissue microarray containing 11,152 prostate cancers." (PMID 25762627, 2015). "TYMS immunostaining was more frequently and more strongly detected in prostate cancers than in normal prostate epithelium suggesting TYMS upregulation in a fraction of tumors." (PMID 25762627, 2015). "Our findings encourage further studies to compare the efficacy of FU-based chemotherapy in prostate cancers and TYMS expression levels of the respective cancers." (PMID 25762627, 2015). "RAD51AP1 and TYMS, co-regulated with a ceRNA network in TNBC, have also been shown to be associated with poor overall survival and recurrence, respectively, in lung and prostate cancers, respectively." (PMID 38473871, 2024). "To further evaluate the relevance of TYMS expression in prostate cancer, we took advantage of our preexisting tissue microarray containing >11,000 prostate cancer specimens with clinical follow up and an attached molecular database, and performed an immunohistochemistry analysis of TYMS expression." (PMID 25762627, 2015). "Immunohistochemical experiments revealed positive TYMS staining in 73% of 10,223 prostate cancers." (PMID 25762627, 2015). "TYMS expression analysis (either alone or in combination with other molecular parameters) might result in clinically useful information in prostate cancer." (PMID 25762627, 2015). "TYMS expression analysis might result in clinically useful information in prostate cancer." (PMID 25762627, 2015). "Moreover, that the prognostic impact of TYMS was independent of established clinical and pathological prognostic features in various models of multivariate analysis applied in this study, further suggests a potential diagnostic utility of TYMS protein measuring in prostate cancer." (PMID 25762627, 2015). "An unfavorable prognosis in prostate cancers with high TYMS expression is not unexpected based on the prognostic impact of TYMS found in various other tumors and also based on the established functions of TYMS." (PMID 25762627, 2015). "In earlier studies, using the same large prostate cancer cohort we had described other very strong and often independent prognostic features such as for example ß3-tubulin, CD57, DAXX, HOXB13, KPNA2, RBM3, mTOR, p62, and TYMS, that might also be worth testing in multiparametric prognostic kits." (PMID 28415558, 2017).